GPC5 (glypican 5)
Description:
Cell surface proteoglycan that bears heparan sulfate.
Tractability: Antibody: its Gene Ontology location is reachable by antibodies, with high confidence; UniProt places it where antibodies can reach, with medium confidence; UniProt predicts a signal peptide or a membrane-spanning region. PROTAC: ubiquitination databases record sites on it.
Gene: Protein-coding gene on chromosome 13 (91,398,621 to 92,873,682, forward strand). Ensembl gene ENSG00000179399.
Subcellular location: Cell membrane; Secreted, extracellular space (Secreted glypican-5)
Subcellular location (Human Protein Atlas): Nucleoplasm; Cytosol
Pathways (Reactome):
Disease: Attachment and Entry; Defective B3GALT6 causes EDSP2 and SEMDJL1; Defective B3GAT3 causes JDSSDHD; Defective B4GALT7 causes EDS, progeroid type; Defective EXT1 causes exostoses 1, TRPS2 and CHDS; Defective EXT2 causes exostoses 2; Dengue Virus Attachment and Entry; Dengue Virus-Host Interactions; RSV-host interactions; Respiratory syncytial virus (RSV) attachment and entry
Metabolism: Glycosaminoglycan-protein linkage region biosynthesis; HS-GAG biosynthesis; HS-GAG degradation
Hemostasis: Initiation of coagulation cascade; Regulation of clotting cascade
Sensory Perception: Retinoid metabolism and transport
Signal Transduction: Release of Hh-Np from the secreting cell
Gene Ontology:
Molecular function: protein binding
Biological process: cell migration; positive regulation of canonical Wnt signaling pathway; regulation of protein localization to membrane; regulation of signal transduction
Cellular component: cell surface; extracellular region; Golgi lumen; lysosomal lumen; membrane; plasma membrane; extracellular matrix
Genetic constraint (gnomAD): Loss-of-function variants: 44 observed, 50.39 expected, observed/expected ratio (o/e) 0.87, 90% interval 0.69 to 1.12. The upper end of that interval is the gene's LOEUF score, 1.12, which puts it in group 4 of 6, group 1 being the genes least tolerant of losing a copy. Missense variants: 724 observed, 706.85 expected, observed/expected ratio (o/e) 1.02, 90% interval 0.96 to 1.09. Synonymous variants: 278 observed, 259.8 expected, observed/expected ratio (o/e) 1.07, 90% interval 0.97 to 1.18.
Homologues: Orthologues: chimpanzee GPC5 (98% identical), macaque GPC5 (97% identical), pig GPC5 (89% identical), rabbit GPC5 (88% identical), dog GPC5 (87% identical), mouse Gpc5 (86% identical), rat Gpc5 (85% identical), zebrafish gpc5a (46% identical), Drosophila melanogaster dally (27% identical), Caenorhabditis elegans gpn-1 (21% identical). Paralogues in human: GPC3 (41% identical), GPC6 (25% identical), GPC4 (24% identical), GPC1 (23% identical), GPC2 (21% identical).
Diseases named in the same sentence as GPC5 in open-access papers:
GPC5 is named in the same sentence as 65 diseases in open-access papers, as found by Europe PMC text mining. Sharing a sentence is not in itself a finding about the gene and the disease. The quoted sentences say what the papers report.
lung carcinoma (16 papers, 2007 to 2025). "Using immunohistochemical staining, the high GPC5 expression level in NSCLC is linked to respiratory symptoms of lung cancer, regional lymph node metastasis, poor differentiation, vascular invasion, and a higher TNM stage." (PMID 34976811, 2021). "Our study observed the variation between gender and found that genotypes “T/T” and “C/C” in rs2352028 of the GPC5 gene are associated with increased lung cancer risk in males (under the overdominant model, after adjusting for age)." (PMID 25999661, 2015). "Our results firstly suggest that polymorphisms in CRP and GPC5 genes have an association with susceptibility risk of lung cancer in the Chinese Han population." (PMID 25999661, 2015). "Cumulatively, our findings provide evidence that polymorphisms in C-reactive protein and Glypican 5 genes are associated with lung cancer risk, and GKN1 determines chemotherapy response in Chinese population." (PMID 25999661, 2015). "We found that the genotypes “T/T” and “C/C” in rs2352028 of the GPC5 gene were associated with increased lung cancer risk in males in the overdominant model." (PMID 25999661, 2015). "The results demonstrated that high GPC5 expression levels in NSCLC were associated with respiratory symptoms in lung cancer diagnosis, poor differentiation, vascular invasion, regional lymph node metastasis and a higher TNM stage." (PMID 24260047, 2013). "Notably, rs2352028 is associated with lower expression of glypican-5 (GPC5), a known lung cancer tumor suppressor." (PMID 40352786, 2025). "The GPC5 rs2352028 variant and lower expression of this gene may contribute to increased risk of lung cancer." (PMID 33302876, 2020). "rs2808630 in CRP and rs2352028 in GPC5 were both associated with lung cancer risk." (PMID 25999661, 2015). "As a result, we prioritized GPC5 c.776C>T (p.Pro259Leu) in GPC5, a known tumor suppressor gene for lung cancer." (PMID 40352786, 2025). "Prevailing studies have indicated that GPC5 functions as a tumor suppressor gene, inhibiting cell proliferation and migration in lung cancer cells." (PMID 40352786, 2025). "GPC5 was found to be overexpressed in the lung cancer phenotype, in lymphoma, and in gastric cancer." (PMID 39484215, 2024). "GPC5 overexpression inhibits lung cancer cell proliferation, migration, and invasion in vitro and slows tumor growth in vivo, whereas GPC5 knockdown reverses these effects." (PMID 34976811, 2021). "While GPC5 expression is downregulated in breast cancer, glioma, hepatocellular carcinoma, lung cancer, pancreatic cancer, prostate cancer, it results in being upregulated in rhabdomyosarcoma." (PMID 32916872, 2020). "We selected seven genes (CRP, GPC5, ACTA2, AGPHD1, SEC14L5, RBMS3, and GKN1) that previously reported link to lung cancer (LC) and genotyped single nucleotide polymorphisms (SNPs) of these genes in a case-control study." (PMID 25999661, 2015). "Patients with high levels of GPC5 expression tended to have respiratory symptoms upon lung cancer diagnosis compared to those with low levels of GPC5 expression (P=0.03)." (PMID 24260047, 2013). "The function of GPC5 has yet to be established and studies of its role in tumors have been limited, although the 13q31–32 amplification has been observed in lung carcinomas, breast tumors, neurological tumors, liposarcomas and rhabdomyosarcomas." (PMID 24260047, 2013). "GPC5 rs2352028 C>T may exert a protective effect on lung cancer patients, and GPC5 rs2352028 may represent a potential genetic marker for the prognosis of lung cancer." (PMID 40352786, 2025). "GPC5 overexpression impaired the lymph node metastasis of lung cancer cells in animal models." (PMID 37830596, 2023). "AhR was translocated into the nucleus from the cytoplasm in GPC5-overexpressing lung cancer cells." (PMID 37830596, 2023). "Furthermore, exosomes originating from GPC5-overexpressing lung cancer cells (GPC5-OE-originated exosomes) had an inhibitory action on LECs, reducing their generation and diffusion." (PMID 35406692, 2022).
lung carcinoma (continued). "Furthermore, GPC5 regulates lung cancer development through a complex pathway network, including FGF-mediated activation of MAPK, PI3K, and STAT pathways." (PMID 32916872, 2020). "Because of a genome-wide association study (GWAS) in never-smokers' lung cancer, GPC5 was firstly linked with lung cancer." (PMID 27806326, 2016). "Since the biological behavior of GPC5 appears totally different in various cancers, we have reason to believe that there might be a unique molecular mechanism utilized by GPC5 in lung cancer." (PMID 27806326, 2016). "The outcomes therefore suggested that GPC5 might affect lung cancer cell migration via regulating the EMT process." (PMID 27806326, 2016). "In addition, a multi-institutional genome-wide association study identified nucleotide polymorphism in the GPC5 gene associated with susceptibility to lung cancer in never smokers." (PMID 27806326, 2016). "A genome-wide association study (GWAS) has reported that genetic variations of GPC5 may contribute to an increased risk of lung cancer in patients who have never smoked." (PMID 24260047, 2013). "It is also demonstrated that gamma-tubulin complex protein-5 (GPC5) competitively bound Wnt3a to inactivate the Wnt/β-catenin signaling pathway and inhibited the EMT of lung cancer cells." (PMID 28798691, 2017). "However, it remains unclear how GPC5 suppresses lung cancer metastasis." (PMID 27806326, 2016). "Although the correlation between glypican-5 (GPC5) and lung cancer is well known, the effect of GPC5 expression on non-small cell lung cancer (NSCLC) survival remains to be determined." (PMID 24260047, 2013). "Previous reports revealed that GPC5 might modulate EMT by preventing β-catenin nuclear localization, thereby preventing lung cancer cells migration and invasion." (PMID 40352786, 2025). "The analysis confirmed that the expression of GPC5 gene was lower in lung cancer tissues compared with adjacent noncancerous tissues." (PMID 27806326, 2016). "While the function of GPC5 remains poorly understood, particularly in MS, different GPC polymorphisms have been reported to increase the risk of lung cancer in non-smokers while decreasing the risk of cancer in MS patients, with this reduced cancer risk stemming from the specific GPC gene." (PMID 32398079, 2020). "In our study, we also detected reduced gene expression levels of GPC5 in PC-3 and DU-145 cells, as opposed to RWPE-1 cell line, which agrees with previously reported findings from breast and lung cancer studies." (PMID 33947326, 2021).
rhabdomyosarcoma (16 papers, 2009 to 2023). A rare aggressive malignant mesenchymal neoplasm arising from skeletal muscle. "GPC5 is highly expressed in rhabdomyosarcomas and promotes a high proliferation rate in the cells of this cancer, while GPC5 acts as a suppressor of tumor growth in the context of non-small-cell lung cancer cells." (PMID 36142190, 2022). "In rhabdomyosarcomas, GPC5 enhances FGF2 signaling that leads to mesodermal cell proliferation without inducing myogenic differentiation." (PMID 32916872, 2020). "Of all the glypicans, GPC3 exhibits the greatest homology with glypican 5 (GPC5), which is located on 13q32, a region of frequent genomic amplification in rhabdomyosarcomas and specifically associated with the PAX7-FOXO1 fusion." (PMID 30873384, 2019). "They revealed that glypican-3 and glypican-5 oppositely regulate the Hedgehog (Hh) signaling in rhabdomyosarcoma cell proliferation." (PMID 25852466, 2015). "For instance, silencing Gpc5 in rhabdomyosarcoma cell lines was shown to decrease the transcription of the Shh target gene Gli1 while depletion of Gpc5 in embryoid bodies increases Shh long-range diffusion and the expression of its target genes Olig2 and Islet1." (PMID 36672161, 2023). "Overexpression of GPC5 may accelerate the tumor progression of lymphoma and may enhance the interaction between Patched 1 and Hedgehog signaling in rhabdomyosarcoma." (PMID 35233466, 2022). "Glypican 5 promotes rhabdomyosarcoma cell proliferation by activating Hh signaling." (PMID 32478377, 2020). "For example, GPC5 could stimulate cell proliferation in rhabdomyosarcoma, which suggested that GPC5 acted as an oncogene." (PMID 27806326, 2016). "In rhabdomyosarcoma, previous studies demonstrated that GPC5 could bind with Hedgehog (Hh) and then activate Hh signaling pathway." (PMID 27806326, 2016). "In this regard, HS20 may be useful for multiple tumor types by targeting different glypicans, such as GPC1 in pancreatic cancer, GPC2 in pre-B cell ALL, and GPC5 in rhabdomyosarcoma." (PMID 26332121, 2015). "Other studies recently showed that GPC5 stimulates the proliferation of rhabdomyosarcoma (RMS) cells and lung metastatic cells in salivary adenoid cystic carcinoma, while GPC5 may be a tumor suppressor in non-small cell lung cancer." (PMID 25978455, 2015). "Glypican-5 was reported also to be modified with chondroitin sulfate in rhabdomyosarcoma cells." (PMID 25852466, 2015). "Studies have shown that GPC5 expression was lower in tumors with a relatively better prognosis, while it was higher in tumors with greater metastatic potential, such as in small cell lung cancer and rhabdomyosarcoma." (PMID 24260047, 2013). "GPC5 is overexpressed in rhabdomyosarcomas (RMS), and down-regulation of GPC5 expression by RNAi decreases the proliferation rate of RMS cells." (PMID 33606708, 2021). "Glypican genes (GPC5 and GPC6), belong to a family of heparan sulfate proteoglycans that are constantly expressed and up-regulated in rhabdomyosarcoma with an amplified 13q31q32 region." (PMID 19759907, 2009).
lung adenocarcinoma (11 papers, 2015 to 2025). A carcinoma that arises from the lung and is characterized by the presence of malignant glandular epithelial cells. "The expression of GPC5 decreased significantly in lung adenocarcinoma tissues, and the low expression of this gene was associated with poor outcomes in lung adenocarcinoma." (PMID 37716978, 2023). "Thus, investigating GPC5 mutations that may be connected to the development of lung adenocarcinoma is vital, offering novel insights into its role in the disease’s pathogenesis." (PMID 40352786, 2025). "Glypican-5 (GPC5) has been well-characterized as a tumor suppressor in lung adenocarcinoma (LUAD); however, the functional implications of its germline mutations in cancer pathogenesis remain largely unexplored." (PMID 40352786, 2025). "The suppressive role of glypican-5 (GPC5) in EMT has been described in lung adenocarcinoma and prostate cancer." (PMID 36358747, 2022). "GPC-5 has been reported as a tumor suppressor gene in many cancers, such as pancreatic cancer, glioma, endometrial cancer, prostate cancer, and lung adenocarcinoma." (PMID 33902495, 2021). "GPC5 was recently reported to be an epigenetically silenced tumour suppressor in lung adenocarcinoma, where it binds Wnt3a at the cell surface to inhibit Wnt/β-catenin signalling." (PMID 29089486, 2017). "Overexpression of GPC5 inhibited proliferation ability in lung adenocarcinoma A549 cells and genes with the function of "positive regulation of cell proliferation" were downregulated." (PMID 27561806, 2016). "Similarly to DACT2, GPC5 is downregulated in lung adenocarcinomas due to significant promoter hypermethylation." (PMID 28870231, 2017). "All the current findings highlight the significance of GPC5 in tumor progression and suggest GPC5 might be an important novel biomarker in lung adenocarcinoma." (PMID 27806326, 2016). "The low expression of GPC5 could predict lymph node metastasis and poor survival of lung adenocarcinoma." (PMID 27806326, 2016). "In consequence, we discovered that over expressing GPC5 could reverse the EMT process in A549 lung adenocarcinoma cell lines." (PMID 27806326, 2016). "In addition, Glypican‐5 (GPC5), downregulated in lung adenocarcinoma, could reduce tumor growth by suppressing Wnt/β‐catenin signaling." (PMID 36621836, 2023). "Interestingly, a genome-wide association study conducted on people who had never smoked revealed a strong correlation between the reduced transcription level of the glypican-5 (GPC5) gene and genotypes of the replicated SNP (rs2352028 at 13q31.3) in lung adenocarcinomas." (PMID 28870231, 2017). "We previously demonstrated that Glypican-5 (GPC5), one of the members of heparan sulfate proteoglycan, was a novel tumor metastasis suppressor in lung adenocarcinoma (LAC)." (PMID 27806326, 2016). "Thus, in hepatocellular carcinoma miR-709 is up-regulated and promotes proliferation, migration, and invasion by targeting glypican-5 (GPC5), a tumor suppressor protein that is highly expressed in lung adenocarcinoma tissue relative to its expression in normal lung tissue." (PMID 26871466, 2016).
prostate carcinoma (7 papers, 2019 to 2024). A carcinoma that arises from epithelial cells of the prostate gland. "There is some evidence that Glypican 5 inhibits the Wnt/β-catenin pathway, such as a study carried out on prostate cancer in which GPC5 was poorly expressed in the cancer cell lines." (PMID 38786073, 2024). "In prostate cancer, GPC5 is downregulated, and its upregulation significantly inhibits cancer cell growth and cell invasion by targeting Sp1 through EMT inhibition and Wnt/β-catenin signaling activation." (PMID 35183057, 2022). "GPC-5 expression was reported to be lower in prostate cancer tissues isolated from 160 patients, as compared to adjacent normal tissue, and low expression levels correlated to poor prognosis." (PMID 31391540, 2019). "GPC-5 mRNA was more abundant in primary prostate epithelial cells than the cancer cells, and these levels tended to decrease in the more metastatic prostate cancer cell lines such as DU-145 and PC-3 cells, as compared to a less metastatic cell line (LNCaP)." (PMID 31391540, 2019). "Of note, GPC-5 expression was lower in prostate cancer tissue, as compared to adjacent normal controls, which also correlated to decrease survival." (PMID 31391540, 2019). "In addition, GPC-5 was reported as a tumor suppressor in prostate cancer but was as an oncogene in lung cancer." (PMID 31391540, 2019). "In contrast, GPC5 protein expression levels examined by immunohistochemistry, are reduced in prostate cancer tissues compared with normal tissues, indicating that GPC5 could represent an additional prostate cancer biomarker." (PMID 33947326, 2021). "GPC1 and GPC5 were predominantly expressed in the normal prostate cell line RWPE-1, whereas GPC1 was the primary member observed in the prostate cancer cell lines PC-3 and DU-145." (PMID 33947326, 2021). "Only GPC-5 and GPC-1 have been studied in prostate cancer, and those studies mainly focused on gene expression and localization in human prostatic tissues via in vitro experiments using a single cell culture." (PMID 31391540, 2019).
non-small cell lung carcinoma (6 papers, 2013 to 2025). A group of at least three distinct histological types of lung cancer, including non-small cell squamous cell carcinoma, adenocarcinoma, and large cell carcinoma. "In order to choose a non-small cell lung cancer cell line for subsequent experiments, we employed various non-small cell lung cancer cell lines to measure the protein expression level of GPC5 via Western blot assays." (PMID 40352786, 2025). "A number of reports point out a tumor suppressor function for GPC5 in several cancers, such as non-small cell lung cancer, lung adenocarcinoma, prostate cancer, pancreatic cancer, and glioma." (PMID 38612755, 2024). "Opposing results show a negative association between GPC5 expression and the progression of non-small cell lung cancer and breast cancer, indicating the necessity of further investigations." (PMID 38612755, 2024). "Upregulation of GPC5 in non-small cell lung cancer was also found promoting cancer cell migration." (PMID 27806326, 2016).
lymphoma (5 papers, 2014 to 2024). A malignant (clonal) proliferation of B- lymphocytes or T- lymphocytes which involves the lymph nodes, bone marrow and/or extranodal sites. "Glypican-5(GPC5), a membrane-associated heparan sulfate proteoglycan (HSPG), plays a crucial role in cell proliferation and metastasis in breast cancer, lymphoma and rhabdosarcoma." (PMID 27806326, 2016).
breast carcinoma (4 papers, 2013 to 2023). "For example, expression of GPC5 showed to be suppressed in different kidney cancers and expression of GPC3 appeared to be downregulated in several thoracic associated cancers including breast cancer." (PMID 36944188, 2023). "However, in breast cancer, GPC5 expression was further decreased in malignant breast tumors in comparison to begin tumors, suggested that GPC5 played a role of tumor suppressor." (PMID 27806326, 2016). "The GPC5 expression levels were reduced in the mammary tumors of breast cancer patients." (PMID 24260047, 2013).